VWF (von Willebrand factor)
Diseases named in the same sentence as VWF in open-access papers (continued):
Sharing a sentence is not in itself a finding about the gene and the disease.
depression (12 papers, 2016 to 2025). "Levels of proteins such as vascular adhesion molecule 1 and von Willebrand factor, which are important in the leukocyte translocation pathway, have been shown to be higher in individuals with depression." (PMID 37600234, 2023). "One of the few tissue-based studies that examined vWF in depression suggested that it was increased in older adults with depression, but this was a very small study (n = 25)." (PMID 37700368, 2023). "Age, symptoms of anxiety or depression, von Willebrand factor, AGEs and c-PWV were included in the multiple regression analysis." (PMID 34830829, 2021). "Increased levels of soluble VCAM-1 and VWF have been reported in other studies in major depression, and support the existence of endothelial damage and cardiovascular risk." (PMID 27598970, 2016). "Consistent with the hypothesis that depression can be secondary to vascular inflammation, plasma vWF levels of patients with major depression, independent on their antidepressant treatment, were significantly higher than those of healthy control subjects." (PMID 32408603, 2020). "In addition, vWF may be considered as a trait marker for MDD as this molecule is consistently higher in patients with depression irrespective of anti-depressant (AD) status." (PMID 33070778, 2020).
Disseminated intravascular coagulation (12 papers, 2014 to 2025). Disseminated intravascular coagulation is characterized by the widespread activation of coagulation, which results in the intravascular formation of fibrin and ultimately thrombotic occlusion of small and midsize vessels. "High-grade neurotoxicity was associated with increased levels of angiotensin II, von Willebrand factor (vWF) and IL-8 (all stored in Weibel-Palade bodies in endothelial cells), and with clinical manifestation of disseminated intravascular coagulation." (PMID 33260966, 2020). "VWF is a marker of endothelial injury and has been demonstrated to be elevated in subjects with disseminated intravascular coagulation." (PMID 35665340, 2022). "Platelets and coagulatory factors such as Von Willebrand Factor are all decorated with blood group antigens, and crosslinking of these components possibly leading to complement activation might account for the link between elevated CL-K1 serum levels and disseminated intravascular coagulation." (PMID 25912189, 2015). "Clinical reports range from mild increased coagulation and fibrinolysis markers such as von Willebrand factor (VWF) and D-dimer levels, to disseminated intravascular coagulation observed in severe avian influenza." (PMID 24884666, 2014).
endotoxemia (12 papers, 2009 to 2025). "Focal necrosis was more relevant in the periportal regions of LPS-exposed rats and associated with immunoreactivity for fibrin, VWF and TM, thus confirming the involvement of the coagulation system and the endothelium in the pathogenesis of liver damage induced by endotoxemia." (PMID 35406712, 2022). "The increase in VWF antigen levels and VWF activity induced by endotoxemia or desmopressin infusion was consistent with previous trials, as was the enhanced platelet plug formation under high shear rates, demonstrating the external validity of the results." (PMID 32636459, 2020). "Similarly, healthy volunteers on prasugrel showed reduced antiplatelet effects due to the increased release of von Willebrand factor during experimental endotoxemia." (PMID 32326325, 2020). "However, the time course of Ang-2 release in the present study was well in line with that of vWF release during endotoxemia." (PMID 19416526, 2009). "Persistent endotoxemia stimulates TNF-alfa production, which leads to ED, increased levels of vWF, FVIII, and PAI synthesized in the endothelium, and platelet hyperactivity, promoting thrombosis." (PMID 39057132, 2024). "The results showed that RMECs extracted from endotoxemia-treated rats of all groups exhibited decreased mRNA expression of the endothelial markers VE-Cadherin, PECAM-1, von Willebrand Factor (vWF), and collagen type IV (Col IV) compared to saline-treated rats." (PMID 36978907, 2023). "Furthermore, by utilizing a mouse model of endotoxemia, we observed that an EPAC1-specific agonist (I942) reduced inflammation-induced vWF secretion in vivo." (PMID 34678311, 2021).
hypothyroidism (12 papers, 2010 to 2025). Abnormally low levels of thyroid hormone. "Increased bleeding time, PT, and aPTT, along with deficiencies of factor VIII and von Willebrand factor (vWF), were reported in patients with overt hypothyroidism, which was reversible after thyroid hormone replacement." (PMID 39006713, 2024). "The observed bruising in this case reflects acquired von Willebrand syndrome due to hypothyroidism, which impairs the synthesis or secretion of vWF, leading to an increased tendency for bruising." (PMID 40084163, 2025). "Endocrine disorders like hypothyroidism can decrease VWF synthesis due to the effects of thyroid hormones on endothelial cells." (PMID 39456826, 2024). "Recent findings show increased bleeding time, PTT, and activated partial thromboplastin time (APTT), alongside reduced FVIII activity and von Willebrand factor (VWF) activity in patients with overt hypothyroidism compared to controls." (PMID 39044871, 2024). "In our study, values of vWF were significantly higher in hyperthyroid patients than in patients with hypothyroidism and euthyroid controls." (PMID 38541980, 2024). "Contrary to these findings, there are studies in the literature reporting that FVIII activity and vWF levels were normal and even increased in patients with hypothyroidism." (PMID 22811708, 2012). "In contrast, subjects with hypothyroidism had lower concentrations vWF antigen and factor VIII together with longer partial thromboplastin time (APTT) that was corrected by treatment with L-thyroxine." (PMID 20181115, 2010). "We would like to emphasize that the coagulation system especially vWF and FVIII, and particularly the anticoagulant system, should be monitored closely in patients followed up for hypothyroidism." (PMID 22811708, 2012). "In the same study, the authors reported that vWF levels and FVIII activity were increased after hypothyroidism treatment." (PMID 22811708, 2012). "In conclusion, we would like to emphasize that the coagulation system especially vWF and FVIII, and particularly the anticoagulant system, should be monitored closely in patients followed up for hypothyroidism." (PMID 22811708, 2012). "In these studies significantly lower values have been found in vWF, FVIII, FIX, FX, and FXI activities in patients with hypothyroidism." (PMID 22811708, 2012). "Significant decreased results were found in children with hypothyroidism in terms of fibrinogen, TT, FVIII, and vWF." (PMID 22811708, 2012).
pancreatic cancer (12 papers, 2008 to 2025). "In a study comprising 194 cancer patients diagnosed between January 2013 and September 2018, gastric, esophageal, colorectal, and pancreatic cancer had significantly higher VWF values compared with the control group." (PMID 38891849, 2024). "The Von Willebrand Factor (VWF) is a marker for angiogenesis, and it has been suggested as a predictive biomarker for therapeutic response in pancreatic cancer." (PMID 33671634, 2021). "As sunitinib treatment inhibits blood vessel formation in cancer, we tested for an anti-angiogenic effect on Ela-myc mice by analyzing the number of blood vessels in pancreatic tumors using von Willebrand factor immunohistochemical staining." (PMID 27374084, 2016). "The attachment of MSC to vascular endothelium was confirmed by immunofluorescence staining of an eGFP-expressing MSC within vWF-positive endothelial cells within a tumour vessel of a pancreatic cancer xenograft." (PMID 18665180, 2008). "We observed significantly higher vWF activity in patients with pancreatic cancer." (PMID 36769870, 2023). "These genes were overlapped with 9,170 DEGs in PAAD, which were obtained by comparing the mRNA expression profile between pancreatic cancer in TCGA and the normal pancreas in GTEx; six specific genes were found, including VWF, GNG11, FGF7, TNXB, IL3RA, and LPAR1." (PMID 37070074, 2023). "An increase in VWF might enhance the metastatic activity of pancreatic cancer and result in a poorer prognosis." (PMID 37070074, 2023). "The ADAMTS‐13/VWF ratio was lowest in those with lung, colorectal and pancreatic cancers." (PMID 31294335, 2019). "Pancreatic cancer thrombosis induced by TF-expressing microvesicles strongly depended on FVIII and FIX, while VWF played a minor role." (PMID 40217494, 2025).
pulmonary hypertension (12 papers, 2010 to 2025). Increased pressure within the pulmonary circulation due to lung or heart disorder. "Elevated plasma levels of vWF and its antigen (vWF:Ag) are associated with short-term prognosis in patients with pulmonary hypertension." (PMID 36553040, 2022). "Adjusted for age, sex, and combined with the ESC/ERS risk score, von Willebrand factor predicted mortality (median follow-up 3.6 years) in pulmonary arterial hypertension with an AUC of 0.94 (sensitivity = 81.3%, and specificity=93.8%)." (PMID 34616545, 2021). "VWF, an adhesive glycoprotein that expressed exclusively in endothelial cells, increased expression levels in pulmonary hypertension caused by hypoxia." (PMID 25543049, 2014). "In IA LPS-exposed lungs at P14, there was an increased ratio of SMA/vWF-stained vessels, indicating increased pulmonary vascular remodeling, which occurs in pulmonary hypertension." (PMID 38481391, 2023). "Emerging evidence suggests that increased degradation of von Willebrand factor and decrease in high molecular weight multimers occurs in patients with pulmonary hypertension (PH)." (PMID 36452355, 2022). "Both of these pulmonary hypertension phenotypes are associated with elevated total plasma levels of FVIII and vWF." (PMID 20174619, 2010).
sickle cell disease (12 papers, 2013 to 2025). Sickle cell anemias are chronic hemolytic diseases that may induce three types of acute accidents: severe anemia, severe bacterial infections, and ischemic vasoocclusive accidents (VOA) caused by sickle-shaped red blood cells obstructing small blood vessels and capillaries. "An increase in VWF and size of VWF multimers has also been reported in sickle cell disease, which needs to be considered during transfusions in these patients." (PMID 37210074, 2023). "In sickle cell anemia, binding to VWF is, in contrast to our results, attributed to a genetic hemoglobin disorder, which manifests as deformed erythrocytes with reduced plasticity." (PMID 30026593, 2018). "We found similar patterns of deposition of vWF in human cerebral small vessels in small vessel vascular dementia, multiple infarct dementia, sickle cell disease, and post-radiation vasculopathy." (PMID 24086636, 2013). "In addition, a positive association between TSP1 and VWF was reported in healthy controls but not in patients with sickle cell disease." (PMID 37255854, 2023).
dementia (11 papers, 2010 to 2025). Loss of intellectual abilities interfering with an individual's social and occupational functions. "High VWF is associated with short-term risk of dementia, possibly due to the increased risk of blood clots restricting blood flow in the brain." (PMID 37198259, 2023). "Along with the effect estimates for ADAMTS13 generally exceeding those of the ADAMTS13:VWF ratio, this renders it unlikely that proteolytic effects of ADAMTS13 on VWF alone are accountable for the association of ADAMTS13 with dementia." (PMID 29615758, 2018). "Cardiovascular health is an important determinant of cognitive decline, but the association of either VWF or ADAMTS13 with risk of dementia is unknown." (PMID 29615758, 2018). "This discrepancy might be attributed to several factors, including differences in sample composition, methods for measuring blood VWF levels, and the statistical approaches used to examine the longitudinal association between VWF levels and cognitive decline or dementia risk." (PMID 40969184, 2025). "vWF has also been associated with markers of cerebral small-vessel (SVD) disease, which is a well-known risk factor for dementia." (PMID 40299555, 2025). "Two meta-analyses suggested potential relationships between blood VWF levels and cognitive impairment or dementia, although results from individual investigations are conflicting." (PMID 40969184, 2025). "It is much less studied in dementia, though recent studies suggest a role for activation of the VWF/ADAMTS13 (von Willebrand factor/ADAM metallopeptidase with thrombospondin type 1 motif 13) axis." (PMID 37941765, 2023). "In conclusion, higher VWF and low ADAMTS13 activity are associated with accelerated cognitive decline and increased risk of dementia." (PMID 29615758, 2018). "Associations of VWF and ADAMTS13 with dementia were mildly attenuated for Alzheimer’s disease only, and broadly unaltered by excluding participants with cardiovascular disease." (PMID 29615758, 2018). "Participants with dementia had higher VWF antigen levels and lower ADAMTS13 activity than individuals without dementia." (PMID 29615758, 2018). "We aimed to determine the cross-sectional and long-term associations of VWF and ADAMTS13 with cognitive decline and dementia risk in a population-based study." (PMID 29615758, 2018). "However, the time-course of the association between VWF and dementia remains unknown, and although ADAMTS13 could aid in disentangling haemostatic effects from associations marking endothelial damage, no published studies about VWF and dementia took into account concurrent ADAMTS13 activity." (PMID 29615758, 2018). "For example, Wolters and colleagues found that higher VWF antigen levels were associated with an increased short-term (within 3 years of follow-up), but not long-term (after 4 years of follow-up), risk of dementia in a population-based study." (PMID 40969184, 2025). "Since most of the identified proteins are not present in both diseases, we performed two independent PPI analyses: the first using the proteins associated with HF (NPPB, REN, ADIPOQ, VWF, ACE, IL6, and CRP) and the second using the proteins involved in dementia (CRP, APP, MAPT, APOE, ACE, and IL6)." (PMID 40699836, 2025). "In this large population-based study, we found that higher VWF antigen levels are associated with prevalence and short-term, but not long-term risk of dementia." (PMID 29615758, 2018). "Increased vWF has been found in heme-rich deposits (HRDs) in patients with dementia." (PMID 20509943, 2010). "However, the association between plasma VWF levels and brain atrophy remains less clear among older adults without dementia." (PMID 40969184, 2025). "However, the association between plasma VWF levels and cognitive decline and neurodegeneration in older adults without dementia remains unclear." (PMID 40969184, 2025).
dementia (continued). "Dementia-related proteins fibronectin (FN), FN1.3, FN1.4, Von Willebrand factor (VWF) and extracellular matrix protein 1 (ECM1) were also measured." (PMID 38397086, 2024). "However, of two studies that assessed the risk of dementia by VWF11,12, neither found baseline VWF antigen levels associated with dementia risk after 4 and 17 years of follow-up, respectively, albeit the latter was hampered by substantial attrition (50%) and lack of cognitive screening at baseline." (PMID 29615758, 2018). "Plasma VWF levels were not correlated with the volumes of the hippocampus among older adults without dementia (r = 0.01; p = 0.82)." (PMID 40969184, 2025). "Plasma VWF levels were not correlated with MMSE score among older adults without dementia (r = −0.004; p = 0.94)." (PMID 40969184, 2025). "Bolstering our confidence in our results using our given sample sizes and clinical diagnoses, another group came to the same conclusion about the presence of an imbalanced VWF/ADAMTS13 axis using a larger group of AD as well as non-AD dementia patients." (PMID 33946285, 2021). "In conclusion, higher VWF and low ADAMTS13 activity are associated with increased risk of dementia, but differences in time-course and lack of synergistic effects may indicate in part independent underlying mechanisms." (PMID 29615758, 2018). "However, associations with VWF are restricted to short-term risks, and do not display synergistic effects with ADAMTS13 on dementia risk." (PMID 29615758, 2018). "The associations of VWF with cognitive decline and risk of dementia were not affected by concurrent ADAMTS13 activity (P-value for the interaction VWF*ADAMTS13 = 0.58 for all-cause dementia and and 0.85 the G-factor)." (PMID 29615758, 2018). "Consequently, the ADAMTS13:VWF ratio was also lower in individuals with dementia, although adjustment for ADAMTS13 did not change the estimates for VWF, and ADAMTS13 did not modify the association of VWF with dementia (P-interaction = 0.93)." (PMID 29615758, 2018).
glioblastoma (11 papers, 2009 to 2025). The most malignant astrocytic tumor (WHO grade IV). "All other studies assessing CD31, VE-cadherin, CD34, VEGFR2, and vWF determined that mRNA expression of these markers was associated with the transdifferentiation of glioblastoma cells to endothelial cells." (PMID 36823554, 2023). "A retrospective data analysis in glioblastomas revealed that pre-operative high VWF levels were associated with a significantly worse post-tumor resection survival and were thought to relate to VWF effects on tumor angiogenesis." (PMID 35327035, 2022). "Representative normal brain and glioblastoma tissue sections with the endothelial marker vWF and TβRIII stained by co-immunofluorescence confirmed a predominant vascular localization both within the normal brain and the glioblastoma sections." (PMID 33772427, 2021). "Frozen, patient‐derived glioblastoma samples were co‐stained with the following antibody combinations: Ang‐2 and vWF, αSMA, or Iba1, respectively." (PMID 26666269, 2016). "The VWF is highly expressed in cancers such as kidney renal clear cell carcinoma, glioblastoma multiforme, and liver hepatocellular carcinoma, while lowly expressed in tumors including colon adenocarcinoma, breast invasive carcinoma, and uterine corpus endometrial carcinoma." (PMID 33968738, 2021). "A fraction of stem-like cells isolated from glioblastomas have been shown to express a number of endothelial cell markers including CD31, CD34, CD105, VE-cadherin, von Willebrand factor (vWF), and VEGF receptor 2 (VEGFR2)." (PMID 36823554, 2023). "The correlation and predictive value of VWF and ADAMTS13 in the prognostication of malignancies such as lung, ovarian, colorectal, glioblastoma, breast, and hematological malignancies have also provided mixed results." (PMID 35327035, 2022).